LCK (LCK proto-oncogene, Src family tyrosine kinase)
Diseases named in the same sentence as LCK in open-access papers (continued):
Sharing a sentence is not in itself a finding about the gene and the disease.
lung carcinoma (13 papers, 2013 to 2025). "We found increased mRNA levels of p21 and a significant decrease in cell cycle-promoting proteins such as CDK2, CDK4, cyclin E1, and cyclin D1, suggesting a possible tumor-suppressing role of LCK in liver and lung cancers." (PMID 36430477, 2022). "In the histopathology-related differences, the adenocarcinoma had significantly higher LCK protein levels than the squamous cell carcinoma in lung cancer and ESCA." (PMID 35069521, 2021). "In addition, LCK expression was also detected in a number of solid cancers including breast, colon and lung cancers." (PMID 34116687, 2021). "We observed positive correlations between three types of NLS and T-cell receptor-associated gene expression signatures, such as CD8A, CD3G, CCL5, TIGT, LCK and IKZF3 in lung cancers and primary melanomas after adjusting clinical factors." (PMID 37100920, 2023). "The presence of LCK and LYN in clusters containing proteins commonly phosphorylated in lung cancer suggest potential pathways of signal transduction." (PMID 23300999, 2013). "LCK, one of the core of LUAD pivotal genes, is an independent predictor of recurrence-free and overall survival in lung cancer patients, which can coordinate the tumor microenvironment with CD3E to promote immunotherapy response and survival in patients with muscle-invasive bladder cancer." (PMID 36744181, 2022). "In a study of lung cancer cell lines using quantitative phosphoproteomics, approximately 40 different kinases were identified as dasatinib targets, including the SFKs LYN, SRC, YES, FYN, and LCK." (PMID 27756880, 2016).
melanoma (9 papers, 2003 to 2025). A malignant, usually aggressive tumor composed of atypical, neoplastic melanocytes. "Survival analysis in both the TCGA cohort and the GSE54467 cohort of melanoma showed that the group with high LCK expression levels was associated with prolonged overall survival (p-value< 0.05)." (PMID 36341345, 2022). "Collectively, in melanoma, LCK is closely linked to the immune components of its microenvironment and is effective in predicting immunotherapeutic response." (PMID 36341345, 2022). "However, it has also been reported that high expression of LCK is associated with increased cumulative survival in melanoma patients." (PMID 36341345, 2022). "To explore the specific role played by LCK in the tumor microenvironment of melanoma, we analyzed the immune landscape of LCK in melanoma." (PMID 36341345, 2022). "We found that the expression level of LCK was significantly higher in melanoma tumor tissues than in normal tissues." (PMID 36341345, 2022). "The results showed that the expression level of LCK was significantly higher in melanoma cell lines (A2058, SKMEL28) than in normal skin cell lines (PIG1, p-value< 0.05)." (PMID 36341345, 2022). "The results suggest that LCK as a ligand acts between the C2 subgroup of melanoma cells and T cell subgroups by binding to the CD8 receptor." (PMID 36341345, 2022). "The findings show that in melanoma, patients with high LCK expression have a higher degree of immune cell infiltration in vivo, which also corresponds to a higher overall survival." (PMID 36341345, 2022). "The results indicated that the expression level of LCK was significantly downregulated as melanoma progressed clinically (p-value< 0.05)." (PMID 36341345, 2022). "As an additional representative from the immune protein category we selected LCK, an Src family tyrosine kinase found on lymphocytes, that was previously identified as a biomarker for good prognosis in melanoma." (PMID 33564068, 2021). "Interestingly, we found that LCK in melanoma cells and T cells facilitates the interaction between the two cells by binding to the CD8 receptor." (PMID 36341345, 2022). "Moreover, the results of RT-qPCR showed that LCK expression was significantly upregulated in melanoma cell lines compared to normal skin cell lines." (PMID 36341345, 2022). "RT-qPCR detected that LCK expression was significantly upregulated in melanoma cell lines." (PMID 36341345, 2022). "We found that LCK, a marker of T cells, plays a crucial role in the immunotherapy of melanoma." (PMID 36341345, 2022). "Therefore, we propose that LCK inhibits immune escape of melanoma cells in melanoma by promoting the activation of T cells." (PMID 36341345, 2022). "In addition, LCK in melanoma cells and T cells further activates T cells by binding to CD8 receptors, promoting anti-tumor response of T cells and suppressing immune escape phenomenon." (PMID 36341345, 2022). "Our findings suggest that LCK may be a novel potential biomarker for predicting immunotherapy in melanoma." (PMID 36341345, 2022). "In conclusion, LCK is a reliable biomarker for melanoma and will contribute to its immunotherapy." (PMID 36341345, 2022). "In addition, LCK was detected in the C2 subgroup of melanoma cells." (PMID 36341345, 2022). "Notably, therapeutic approaches that target LCK in tumor cells may offer a new perspective for the treatment of melanoma." (PMID 36341345, 2022). "Melanoma, head and neck, and bladder tumors expressing high levels of FLT3LG.mod, PDCD1.mod and FOXP3.mod transcripts, respectively, also expressed significantly higher levels of LCK protein." (PMID 26398410, 2015).
asthma (8 papers, 2021 to 2025). "c-CBL alleviated asthma and suppressed Th2 differentiation by facilitating LCK ubiquitination, interrupting c-JUN activation and CD28 expression in vivo and in vitro." (PMID 39342146, 2024). "Intranasal delivery of small molecule pharmacological inhibitor is more relevant to human asthma and likely to mitigate side effects produced by the global inhibition of LCK using systemic therapy." (PMID 36144198, 2022). "We therefore examined in situ LCK(Y505) phosphorylation in CD4+ T cells from the lung sections obtained from our mouse asthma model and observed increased phospho-LCK (Y505) staining in CD4+ T cells from Asp-challenged Spry2−/− mice." (PMID 33684096, 2021). "LCK drives T-cell receptor signaling to promote Th2 polarization and cytokine release (e.g., IL-4 and IL-13), directly exacerbating IgE-mediated allergic inflammation in diseases such as asthma and atopic dermatitis." (PMID 40649880, 2025). "This suggested that the decreased expression of c-CBL may contributed to LCK function in Th2 differentiation and asthma development." (PMID 39342146, 2024). "Inhibition of LCK mitigated airway inflammation and Th2 development in asthma mice." (PMID 39342146, 2024). "The LCK inhibition approach was tested in an ovalbumin asthma model in mice earlier." (PMID 36144198, 2022). "In addition, therapies targeting LCK have been shown to promote/inhibit T-cell growth and development in a variety of diseases such as type 1 diabetes, colon cancer, asthma, and organ transplant rejection, thereby altering disease outcomes." (PMID 35754830, 2022). "LCK may play an important role inflammatory pulmonary diseases such as asthma as it is well-known that LCK controls expression and release of various allergic cytokines through differentiation/polarization of Th2 cell subtype." (PMID 36144198, 2022). "Since LCK plays a vital role in T cell signaling and cytokine production, alteration in activity or expression of LCK may be involved in various disease progressions, including atherosclerosis, ulcerative colitis, psoriasis, rheumatoid arthritis, diabetes, asthma, and cancer." (PMID 36568106, 2022). "It suggested that c-JUN and ETS1 may be involved in regulation of asthma development and Th2 differentiation by controlling CD28 expression, and LCK may function by control c-JUN/ETS1/CD28 axis." (PMID 39342146, 2024). "c-CBL/LCK/c-JUN/ETS1/CD28 axis was partially involved in childhood asthma, and may provide novel insights for clinical treatment for asthma." (PMID 39342146, 2024). "c-CBL/LCK/c-JUN/ETS1/CD28 axis was beneficial for asthma, and may provide novel targets for asthma therapy." (PMID 39342146, 2024). "Additionally, uPAR overexpression universally caused changes in the expression of genes related to cellular proliferation (BRICD5) and T‐cell/B‐cell signaling (LCK/LIME1) and importantly asthma via the IL33 receptor (IL1RL1), now a target for new asthma drugs." (PMID 37876037, 2023). "Further, our study emphasizes the role of LCK signaling in an allergic model relevant to human asthma, unlike ovalbumin which is not a natural allergen." (PMID 36144198, 2022).
autoimmune disease (8 papers, 2013 to 2026). A disorder resulting from loss of function or tissue destruction of an organ or multiple organs, arising from humoral or cellular immune responses of the individual to their own tissue constituents. "Co-receptor-associated LCK plays distinct roles in responding to high- versus low-affinity antigens presenting a potential therapeutic window for autoimmune diseases." (PMID 41601693, 2026). "Down regulation of CD247 and LCK has been associated with other autoimmune diseases, tumours and chronic infections all of which are associated with persistent exposure to antigen." (PMID 23977094, 2013). "The differential role of co-receptor-bound LCK in the response to high- and low-affinity antigens could be potentially used for the development of novel strategies for treating autoimmune diseases." (PMID 36564464, 2023). "On the basis of these results and given the wide use of GCs in autoimmune diseases and their various side effects, it might be interesting to study the effect of GCs in combination with LCK inhibition in this context." (PMID 36490346, 2022). "Therefore, selective inhibition of LCK can be used to treat T cell-mediated autoimmune diseases, inflammatory diseases, and organ transplant rejection." (PMID 33159014, 2020). "Despite the fact that LCK is the best studied LYP substrate, it appears that LYP dephosphorylation of LCK does not explain the contribution of LYP to autoimmune disorders." (PMID 39342392, 2024).
Immunodeficiency (8 papers, 2016 to 2024). Failure of the immune system to protect the body adequately from infection, due to the absence or insufficiency of some component process or substance. "Another previous report that described an L341P LCK mutation concluded that there was a complete loss of kinase activity, explaining the T cell immunodeficiency." (PMID 37962568, 2024). "Further, two reports of immune deficiency with reduced LCK protein expression and the presence of an aberrant isoform of LCK mRNA missing exon 7 have been published." (PMID 38100037, 2023). "In LCK-deficient patients with combined immunodeficiency, low CD4 expression serves as a specific hallmark." (PMID 38112969, 2023). "DOK3 interacts with LCK, the respective LCK deficiency is characterized by several phenotypes (diarrhea, immunodeficiency, T-cell lymphopenia) closely related to those of our patient." (PMID 33893283, 2021). "Mutation of CDK4 was found to be associated with a variety of cancers and mutation of LCK was found to be associated with immunodeficiency." (PMID 26895224, 2016). "Additionally, deregulated LCK expression has been associated with genetically undefined immune deficiencies and hematological malignancies." (PMID 38100037, 2023). "The P440S LCK variant caused protein structural instability and partial LOF, leading to immunodeficiency due to “hypoactive” T cells (defective TCR-signal transduction) and immune dysregulation due to residual T cell proliferation and cytokine production (CID with autoimmunity)." (PMID 37962568, 2024). "Immunodeficiencies caused by the lack of LCK activity lead to T cells that are low in number and non-responsive, which in turn causes susceptibility to infections." (PMID 28448599, 2017).
colon carcinoma (7 papers, 2015 to 2022). "A closer look at the severity of the tumor growth revealed that in Vil/Cre mice, colon tumor development was limited to hyperplasia, while WT, CerS4 KO, and CerS4 LCK/Cre mice also showed dysplasia and neoplasia." (PMID 35163788, 2022). "Furthermore, there is evidence that nitration of proteins such as CCL2 and LCK decreases the number of tumour-infiltrating T cells in colon cancer and it skews them towards an unresponsive phenotype in prostate cancer." (PMID 35660630, 2022). "Interestingly, CerS4 LCK/Cre mice developed significantly more colon tumors than CerS4 WT, CerS4 KO, and CerS4 Vil/Cre mice." (PMID 35163788, 2022). "Histological analysis of colon tumors by multiepitope ligand cartography (MELC) exhibited a high abundance of immune cells in colon tissue of AOM/DSS-treated WT and CerS4 LCK-Cre mice." (PMID 35163788, 2022).
COVID-19 (7 papers, 2022 to 2025). A disease caused by infection with severe acute respiratory syndrome coronavirus 2. "Results from the autopsy of lungs from obese COVID-19 patients showed upregulation of the lymphocyte-specific kinase (LCK) and early growth response 2 (EGR2) genes." (PMID 37408184, 2023). "We observed that the COVID-19 ICU patients had activated T cell and B cell signaling characterized with activation of the tyrosine kinases LCK, LYN, and SYK." (PMID 38389037, 2024). "Jing Fang Bai Du San was found to temporarily improve the clinical symptoms of patients, and network pharmacology analysis initially revealed that the targets of Jing Fang Bai Du San in the treatment of COVID-19 mainly included EGFR, PIK3CA, LCK, and MAPK1." (PMID 36782331, 2023). "The area under the curve (AUC) values for 6 shared hub genes (CDC6, PLCG1, KIF15, LCK, CDC25C, and RASGRP1) in the SLE dataset to discriminate between patients and healthy controls were greater than 0.61, while those for the COVID-19 dataset were greater than 0.91." (PMID 37426642, 2023).
Sepsis (7 papers, 2020 to 2023). Sepsis is defined as life-threatening organ dysfunction caused by a dysregulated host response to infection. "Overall, through mouse study and online patient data analysis, five genes (CD247, DOCK2, IFI35, ITK, and LCK) were reported to positively correlate with sepsis prognosis whilst only the expression of MED25 displayed a negative correlation." (PMID 37456011, 2023). "We also found that the expression level of CD3D, CD3E, CD4, CD28, IL7R, and LCK was statistically different between sepsis and normal groups, indicating their potential role in the development of sepsis." (PMID 37113759, 2023). "The results showed the expression level of CD3D, CD3E, CD4, CD28, IL7R, and LCK was statistically different between sepsis and normal groups." (PMID 37113759, 2023). "The lower expression of the hub genes (CD3D, CD3E, CD4, CD28, IL7R and LCK) was observed in sepsis samples, which was consistent in all the six hub genes." (PMID 37113759, 2023). "The lower expression of the six hub genes (CD28, CD3D, CD4, IL7R, LCK, and CD3E) was observed in sepsis samples." (PMID 37113759, 2023). "The results suggested that the expressions of LCK and CCL5 were significantly higher in normal samples than in samples from patients with sepsis, while the expressions of ITGAM and MMP9 were significantly lower in normal samples than in samples from patients with sepsis in the GSE57065 dataset." (PMID 35184762, 2022). "CD247, DOCK2, IFI35, ITK, LCK, and MED25 might be important targets affecting the prognosis of sepsis." (PMID 33015708, 2020). "In our study, the expression of LCK and FYN was decreased in patients with sepsis, indicating possible suppression of T-cells and NK cells, as well as a role for these proteins in platelet functions during sepsis, which warrants further exploration." (PMID 33132754, 2020). "Sepsis development/progression in mice could be regulated by changing the LPS amount, as an example of using different doses of LPS to set survival and death groups in the discovery of six genes (CD247, DOCK2, IFI35, ITK, LCK and MED25)." (PMID 37456011, 2023). "Finally, we identified a four-gene signature, containing the hub genes LCK, CCL5, ITGAM, and MMP9, and established a model that could be used to diagnose patients with sepsis." (PMID 35184762, 2022). "However, the roles of LCK and FYN in sepsis have not been entirely elucidated." (PMID 33132754, 2020).
lymphoma (6 papers, 2021 to 2025). A malignant (clonal) proliferation of B- lymphocytes or T- lymphocytes which involves the lymph nodes, bone marrow and/or extranodal sites. "It was next important to determine the role of Unc119 in TCR signal transduction, and so, we formed immune conjugates in vitro using OTI CD8+ T cells and SIINFEKL-expressing EG.7 lymphoma cells and quantified the polarisation of total LCK and pLCK Y394 to the IS as represented schematically." (PMID 39814552, 2025). "Of note, the pattern of LCK expression is similar to oncogenes SYK and BTK, which are known drivers of B-cell leukemia and lymphoma." (PMID 36711753, 2023). "Among the rest non-hematologic and non-lymphoid cancer types, we found that both the CD20 and LCK protein levels were high in the stomach adenocarcinoma (STAD)." (PMID 35069521, 2021).